UGT1A6 (UDP glucuronosyltransferase family 1 member A6)
Description:
[Isoform 1]: UDP-glucuronosyltransferase (UGT) that catalyzes phase II biotransformation reactions in which lipophilic substrates are conjugated with glucuronic acid to facilitate their inactivation and excretion from the body. Essential for the elimination and detoxification of drugs, xenobiotics and endogenous compounds. Involved in the glucuronidation of arachidonic acid (AA) and AA-derived eicosanoids including 15-HETE and 20-HETE. Conjugates small planar phenolic molecules such as 4-nitrophenol, 1-naphthol, and 4-methylumbelliferone. The bulky phenol 4-hydroxybiphenyl, androgens and estrogens are not substrates. 2-hydroxybiphenyl is an excellent substrate (By similarity). Involved in the glucuronidation of the phytochemical ferulic acid at the phenolic or the carboxylic acid group. [Isoform 3]: Isoform 3 lacks transferase activity but acts as a negative regulator of isoform 1.
Synonyms: UDPGT 1-6; UGT1-06; UGT1.6; UGT-1F; UGT1F; GNT1; HLUGP; HLUGP1; UGT1A6S
Tractability: Small molecule: a high-quality ligand is known. Antibody: UniProt predicts a signal peptide or a membrane-spanning region. PROTAC: its protein half-life has been measured; a small molecule that binds it is known.
Target class: Enzyme; Transferase
Safety:
Unwanted effects reported when the protein is acted on. In parentheses: how it was acted on, where the effect was seen, and who reports it.
adverse drug reactions (source: ClinPGx)
adverse reactions (source: ClinPGx)
better response (source: ClinPGx)
cardiotoxicity (source: ClinPGx)
hand-foot syndrome (source: ClinPGx)
hyperbilirubinemia (source: ClinPGx)
hyperprolactinemia (source: ClinPGx)
liver failure (source: ClinPGx)
nephrolithiasis (source: ClinPGx)
neutropenia (source: ClinPGx)
severe neutropenia (source: ClinPGx)
vomiting (source: ClinPGx)
worse response (source: ClinPGx)
Gene: Protein-coding gene on chromosome 2 (233,691,607 to 233,773,300, forward strand). Ensembl gene ENSG00000167165.
Subcellular location: Microsome; Endoplasmic reticulum membrane
Subcellular location (Human Protein Atlas): Vesicles; Endoplasmic reticulum
Pathways (Reactome):
Drug ADME: Aspirin ADME; Paracetamol ADME
Metabolism: Glucuronidation
Gene Ontology:
Molecular function: enzyme binding; glucuronosyltransferase activity; protein homodimerization activity; retinoic acid binding; enzyme inhibitor activity; protein heterodimerization activity; UDP-glycosyltransferase activity
Biological process: xenobiotic metabolic process; cellular response to glucocorticoid stimulus; estrogen metabolic process; flavone metabolic process; glucuronate metabolic process; liver development; monocarboxylic acid metabolic process
Cellular component: endoplasmic reticulum; endoplasmic reticulum membrane
Genetic constraint (gnomAD): Loss-of-function variants: 32 observed, 46.51 expected, observed/expected ratio (o/e) 0.69, 90% interval 0.52 to 0.92. The upper end of that interval is the gene's LOEUF score, 0.92, which puts it in group 3 of 6, group 1 being the genes least tolerant of losing a copy. Missense variants: 685 observed, 696.14 expected, observed/expected ratio (o/e) 0.98, 90% interval 0.92 to 1.05. Synonymous variants: 238 observed, 263.11 expected, observed/expected ratio (o/e) 0.9, 90% interval 0.81 to 1.01.
Homologues: Orthologues: guinea pig UGT1A6 (81% identical), mouse Ugt1a6a (80% identical), mouse Ugt1a6b (79% identical), zebrafish ugt2a7 (40% identical), zebrafish si:ch73-334d15.1 (39% identical), zebrafish ugt2b5 (39% identical), zebrafish ugt2b1 (38% identical), zebrafish ugt5a2 (36% identical), zebrafish ugt5c1 (36% identical), zebrafish ugt5g1 (36% identical), zebrafish ugt5b4 (36% identical), zebrafish ugt5b1 (36% identical), and 96 more. Paralogues in human: UGT1A1 (69% identical), UGT1A7 (68% identical), UGT1A9 (68% identical), UGT1A10 (68% identical), UGT1A8 (68% identical), UGT1A4 (67% identical), UGT1A3 (67% identical), UGT1A5 (67% identical), UGT2B10 (43% identical), UGT2B17 (42% identical), UGT2B11 (42% identical), UGT2B15 (42% identical), and 9 more.
Diseases named in the same sentence as UGT1A6 in open-access papers:
UGT1A6 is named in the same sentence as 34 diseases in open-access papers, as found by Europe PMC text mining. Sharing a sentence is not in itself a finding about the gene and the disease. The quoted sentences say what the papers report.
colorectal cancer (6 papers, 2016 to 2022). A primary or metastatic malignant neoplasm that affects the colon or rectum. "UGT1A6 gene polymorphism rs2070959 was found to be associated with colon and colorectal cancer." (PMID 35629166, 2022). "Colorectal cancer patients with the UGT1A6 rs2070959 AA genotype may have an increased risk for severe neutropenia when treated with irinotecan compared to patients with the wild-type UGT1A6 rs2070959 GG genotype." (PMID 34198586, 2021). "In a study of 1600 colorectal cancer patients and 2500 unaffected siblings, the variation in 4 UGT genes (UGT1A3, UGT1A6, UGT2B4, and UGT2B15) modified risk of colorectal cancer either independently of interactively with nonsteroidal anti-inflammatory use." (PMID 27881391, 2017).
lung carcinoma (5 papers, 2012 to 2023). "Eight UGT1A6 polymorphisms were sequenced in a test set of 72 Chinese lung cancer patients and 62 healthy controls." (PMID 22912755, 2012). "In this study, we had demonstrated that individuals with UGT1A6*2 (haplotype #2 and 6) had increased lung cancer risk." (PMID 22912755, 2012). "UGT1A6 19T>G, 541A>G and 552A>C remained associated with increased lung cancer risk, and UGT1A6 105C>T and IVS1+130G>T remained significantly associated with reduced lung cancer risk." (PMID 22912755, 2012). "UGT1A6 19T>G, 541A>G and 552A>C showed significant association with increased lung cancer risk, while UGT1A6 105C>T and IVS1+130G>T were significantly associated with reduced lung cancer risk." (PMID 22912755, 2012). "The purpose of this study was to evaluate the association of UGT1A6 polymorphisms and haplotypes with lung cancer risk and to evaluate the functional significance of UGT1A6 polymorphisms." (PMID 22912755, 2012). "It is unclear how UGT1A6 IVS1+130G>T modulates lung cancer risk as it is located in the first intronic region of the UGT1A6 gene." (PMID 22912755, 2012). "Functional test demonstrated that UGT1A6 105C>T increased mRNA stability, providing a plausible explanation of its association with reduced lung cancer risk." (PMID 22912755, 2012). "UGT1A6 105C>T was demonstrated to increase mRNA stability, providing a plausible explanation of its association with reduced lung cancer risk." (PMID 22912755, 2012). "UGT1A6 IVS1+130G>T was found to be the only SNP associated with decreased risk of lung cancer in multivariate analysis." (PMID 22912755, 2012). "Polymorphisms in the UGT1A6 gene in lung tissue and qualitative or quantitative alterations in humans may increase the likelihood of lung cancer in the population." (PMID 36741721, 2022). "We hypothesized that polymorphisms in the UGT1A6 may affect the ability to detoxify lung cancer carcinogens and modulate lung cancer risk." (PMID 22912755, 2012). "Our study suggests that UGT1A6 genotyping may be integrated into lung cancer screening strategy to help identify susceptible populations." (PMID 22912755, 2012). "This is the first study to describe the association between UGT1A6 polymorphisms and lung cancer." (PMID 22912755, 2012). "Quantitative or qualitative alterations in UGT1A6 expression may affect the rate of glucuronidation, thereby modifying the risk of developing lung cancer." (PMID 22912755, 2012). "Thus UGT1A6 polymorphisms may be used to identify people with increased risk of developing lung cancer." (PMID 22912755, 2012). "In conclusion, this study suggests that UGT1A6 polymorphisms may modulate lung cancer risk." (PMID 22912755, 2012). "Elevated expression of UGT1A6 in kidney, liver, and lung cancers compared with normal tissues has different prognostic implications for patients with different cancers." (PMID 36741721, 2022). "In kidney and liver cancers, the higher the expression of UGT1A6, the shorter the overall survival of patients; while in lung cancer, the higher the expression of UGT1A6, the better the prognosis of patients." (PMID 36741721, 2022). "Two polymorphisms UGT1A6 105C>T and IVS1+130G>T were found to be associated with reduced lung cancer risk." (PMID 22912755, 2012). "UGT1A6 552A>C was in close LD with UGT1A6 541A>G (D′ = 0.9706, r2 = 0.7795) in lung cancer patients." (PMID 22912755, 2012). "UGT1A6 19T>G, 541A>G and 552A>C were associated with increased lung cancer risk, whereas UGT1A6 105C>T and IVS1+130G>T were inversely associated with lung cancer risk." (PMID 22912755, 2012). "Moreover, the increased expression of UGT1A6 is also characteristic of patients with cancers, including lung cancers." (PMID 38203636, 2023). "This tentatively suggests that UGT1A6 may play an oncogenic role in kidney and liver cancers, while the effect of UGT1A6 on cancer progression in lung cancer needs to be further explored." (PMID 36741721, 2022).
lung carcinoma (continued). "Meta-analysis of 6 hub genes of lung cancer was performed by ONCOMINE databases, and showed that UGT1A6 and DGAT1 were upregulated, while HPGDS and LPL were downregulated." (PMID 33050938, 2020).
breast carcinoma (4 papers, 2012 to 2022). "It was worth noting that the UGT1A6 is highly expressed in the TamR group, indicating that the UDP-glucuronyl transferase encoded by UGT1A6 also played an important role in TAM-resistance invasive lobular breast cancer cells." (PMID 34886806, 2021). "The role of a UGT1A6 variant for breast cancer risk is reasonable because a reduction of enzyme activity has been previously suggested." (PMID 23781229, 2013). "Two functional genetic variants rs6759892 and rs2070959 which are located in the UGT1A6 have been suggested to affect overall breast cancer risk." (PMID 23226154, 2012). "The UGT1A6 gene polymorphism is associated with breast carcinogenesis in the European population, and people with the UGT1A6-19-GC genotype have an increased risk of developing breast cancer." (PMID 36741721, 2022). "People with UGT1A6-19-gc have an increased risk of breast cancer." (PMID 36741721, 2022). "UGT1A6 also conjugates exogenous compounds which occur in the environment and in food, e.g., 4-ethylphenol or in drugs, e.g., acetaminophen, which together with other UGT1A6 substrates have been suggested to affect breast cancer risk." (PMID 23781229, 2013). "Therefore, it will be of particular interest to evaluate the UGT1A6 polymorphism in concert with all known risk factors in large study collections to establish a more comprehensive breast cancer susceptibility panel." (PMID 23781229, 2013). "To validate the roles of UGT1A6 polymorphisms in breast cancer risk we conducted an independent confirmatory study and a pooled analysis with more than 7000 patients and 8000 controls, and report the association between the UGT1A6_19_GG genotype and an increased overall breast cancer risk." (PMID 23781229, 2013). "Moreover, it is well known that UGT1A6 is involved in the conjugation of steroid hormones and increased levels of sex hormones are a known risk factor for breast cancer." (PMID 23781229, 2013).
adenoma (3 papers, 2015 to 2023). A neoplasm arising from the epithelium. "Independent of aspirin use, the UGT1A6 variants have been reported to influence adenoma recurrence and CRC risk." (PMID 25927723, 2015). "Modifying effects of UGT1A6 genotype have been reported in some studies of adenomas but not others, and not in studies of colon cancer." (PMID 25927723, 2015).
bladder cancer (3 papers, 2013 to 2020). "The increased expression of UGT1A6 in bladder tissue can lead to enhanced removal of carcinogens dissociated from glucoronids from bladder tissue into the urine, thereby reducing bladder cancer risk." (PMID 23752272, 2013). "When analyzing 12 susceptible loci in relation to bladder cancer, two most notably showed significant additive gene-environment interactions: NAT2 (P = 7×10-4) and UGT1A6 (P = 8×10-4)." (PMID 27690298, 2017). "Due to increased expression of UGT1A6.1, the SNP rs17863783 was concluded to be protective against bladder cancer." (PMID 27690298, 2017). "Moreover, the Nrf2-mediated protection against bladder cancer was attributed to increased metabolism of BBN by Ugt1a6." (PMID 33276631, 2020).
Cirrhosis (3 papers, 2021 to 2023). A chronic disorder of the liver in which liver tissue becomes scarred and is partially replaced by regenerative nodules and fibrotic tissue resulting in loss of liver function. "Targets affected only by NAFLD-associated cirrhosis were CYP2C8,MGST1, MGST3, UGT2B4, FMO5, and BSEP, while targets that showed asignificant reduction only with cancer-associated cirrhosis were CYP2E1and UGT1A6." (PMID 34428046, 2021). "The relative expression of UGT1A6 was notably associated with cirrhosis and serum AFP." (PMID 34337056, 2021).
brain injury (2 papers, 2017 to 2021). Acute and chronic (see also brain INJURIES, CHRONIC) injuries to the brain, including the cerebral hemispheres, CEREBELLUM, and brain STEM. "Another study reported a third inducible UGT1A6 variant (i.e., 19T > G) as well as a CYP2C9 variant in VPA-treated patients with severe traumatic brain injury." (PMID 34468892, 2021).
childhood cancer (2 papers, 2021 to 2022). "It has been reported that the UGT1A6 variant (T-allele) is associated with a significantly increased risk of cardiotoxicity in childhood cancer survivors (p = 0.0062, OR = 7.98, 95% CI: 1.85–34.4)." (PMID 33854429, 2021). "Pharmacogenomic testing is recommended for childhood cancer patients with indication for the anthracyclines daunorubicin and doxorubicin for specific variants of RARG, SLC28A3 and UGT1A6*4." (PMID 35872888, 2022).
colon cancer (2 papers, 2016 to 2018). "In summary, our results suggest variant alleles of the genes involved in aspirin pathways, CYP2C9, ODC1 and UGT1A6, may be involved in the modification of CRC or colon cancer risk independently or in conjunction with aspirin use." (PMID 29425227, 2018). "Upon assessing GxE interaction, aspirin-only users with wild-type genotype of the SNPs in UGT1A6 gene gave suggestive evidence of decreased risk of CRC or colon cancer but not in variant allele carriers." (PMID 29425227, 2018). "Additionally, the site-specific interaction of UGT1A6 SNPs with colon cancer has been observed previously, albeit without statistical significance due to small study size consisting of only 422 cases and 481 population controls." (PMID 29425227, 2018).
epilepsy (2 papers, 2021 to 2023). A brain disorder characterized by episodes of abnormally increased neuronal discharge resulting in transient episodes of sensory or motor neurological dysfunction, or psychic dysfunction. "A study of VPA monotherapy and stable control of epileptic seizures in patients with epilepsy showed that carriers of SNVs UGT1A6*3 (rs6759892; 19T>G), UGT1A6*5 (rs2070959; 541A>G) and UGT1A6*9 (rs1105879; 552A>C) had a reduction in blood levels of VPA therapeutic metabolites." (PMID 36677060, 2023).
maturity onset diabetes (2 papers, 2017 to 2023). "In both male and female type 2 diabetes-induced Sprague–Dawley rats treated with streptozotocin, consumption of a high-fat diet increased UGT1A1, UGT1A6, and UGT1A7 probe activities but decreased the UGT2B1 probe activity." (PMID 37034183, 2023).
cardiomyopathy (1 paper, 2025). A disease of the heart muscle or myocardium proper. "The rs17863783 variant in the UGT1A6 gene was also reported to be associated with a greater risk of cardiomyopathy." (PMID 40413218, 2025). "Carrying the A allele in the SLC28A3- rs7853758 variant was associated with a lower risk of cardiomyopathy (OR = 0.36, 95% CI: 0.22–0.60), and the variant UGT1A6-rs17863783 was significantly associated with a 6.2-fold (95% CI: 2.5–15.4; p = 1.1 × 10−4) increased risk of severe cardiomyopathy." (PMID 40413218, 2025).
colorectal adenoma (1 paper, 2018). An adenoma that arises from the colon or rectum. "In previous studies, a significant interaction between UGT1A6 SNPs, aspirin use and colorectal adenoma risk has been observed whereby, carriers of variant allele were associated with lower risk of colorectal adenoma in aspirin users compared to non-users." (PMID 29425227, 2018).
Hepatic steatosis (1 paper, 2013). Steatosis is a term used to denote lipid accumulation within hepatocytes. "Mice on high-fat and high-sucrose diet, which develop severe hepatic steatosis, display elevated expression of Ugt1a1 and Ugt1a6 mediated by CAR and PXR." (PMID 23346097, 2013).
neuroblastoma (1 paper, 2021). Neuroblastoma (NB) is the most common solid, extracranial childhood tumor. "In the present paper, we demonstrate that using a specific neuroblastoma cells co-expressing NQO2 and the conjugating enzyme UGT1A6 together with original analytical methods, that the association of these two enzymes permit NQO2 to perform its detoxifying theoretical duty towards menadione." (PMID 34040527, 2021).
pulmonary fibrosis (1 paper, 2023). Chronic progressive interstitial lung disorder characterized by the replacement of the lung tissue by connective tissue, leading to progressive dyspnea, respiratory failure, or right heart failure. "Interestingly, the UGT1A6 gene, whose variations in expression and methylation were observed, is also significantly associated with the development of pulmonary fibrosis." (PMID 38203636, 2023).
cancer (8 papers, 2018 to 2025). A tumor composed of atypical neoplastic, often pleomorphic cells that invade other tissues. "These actions may stem from the influence of vitamin D on the expression of genes associated with collagen production, such as SHMT1, UGT1A6, and ITIH2.The anti-cancer properties of vitamin D are also supported by changes in KLHL3 and TTPA gene expression." (PMID 38203636, 2023). "Therefore, it is believed that altering the expression of UGT1A genes, including UGT1A6, can significantly modulate the response to the treatment, development, and progression of cancer." (PMID 38203636, 2023). "UGTs genes are upregulated in tissues associated with drug metabolism, such as cancers of the liver, kidney, intestine, and pancreas, such as UGT1A6, UGT1A9, UGT1A10, UGT2A3, UGT2B7, and UGT8, and they are significantly associated with increased overall survival in cancer." (PMID 36741721, 2022). "Notably, UGT8 and UGT1A6 showed high expression in 18 and 13 different cancer types, respectively." (PMID 34503303, 2021). "Kaplan–Meier plots and logrank tests revealed that six UGT genes were significantly associated with increased overall survival (OS) rates [UGT1A1 (LUSC), UGT1A6 (ACC), UGT1A7 (ACC), UGT2A3 (KIRC), UGT2B15 (BLCA, SKCM)] or decreased OS rates [UGT2B15 (LGG), UGT8 (UVM)] in specific cancers." (PMID 34503303, 2021).
tumor (4 papers, 2020 to 2025). "UGT1A6 was strongly positive in normal renal tissues (renal tubular cells were highly stained) but weakly or moderately positive in tumor tissues after CAB009819 staining." (PMID 37056387, 2023). "The expression of UGT1A1, UGT1A6, and UGT1A10 increased as the tumor progressed, suggesting that the UGT1A gene family plays an important role in the tumorigenesis and progression of PC." (PMID 34595239, 2021).
infection (1 paper, 2019). The state of being infected such as from the introduction of a foreign agent such as serum, vaccine, antigenic substance or organism. "On the other hand, Cyp1a2, Cyp3a25, Ugt1a6 and Ugt1a9, although down-regulated at 8 days post-infection, showed minimal effects at 6 and 12 days post-infection." (PMID 31299982, 2019).
UGT1A6 also shares sentences with these, for which no sentence is quoted: Ataxia (3 papers); pancreatitis (3); acute liver failure (1); breast tumors (1); cholelithiasis (1); colon adenocarcinoma (1); epileptic seizures (1); Gilbert syndrome (1); glioblastoma (1); head and neck cancer (1); Hepatitis (1); liver cancer (1); metabolic syndrome (1); neutropenia (1); panic attacks (1).